NRG1 (neuregulin 1)
Diseases named in the same sentence as NRG1 in open-access papers (continued):
Sharing a sentence is not in itself a finding about the gene and the disease.
depression (30 papers, 2012 to 2026). "Serum NRG-1 levels are significantly lower among depressed patients compared with controls, and NRG1 SNPs (single-nucleotide polymorphisms) are associated with depression and BD." (PMID 40869303, 2025). "Functional mapping to the human brain regions showed NRG1 to have high expression in the main subcortical limbic brain regions implicated in depression." (PMID 37583471, 2023). "A clinical study with 267 MDD patients suggested that NRG1-linked white matter abnormalities were associated with clinical symptoms of depression and anxiety." (PMID 37583471, 2023). "Several clinical and genetic association studies have reported the linkage between NRG1 gene variations and susceptibility to different psychiatric disorders including depression." (PMID 37583471, 2023). "A recent GWAS study of 246,363 patients with depression and MAGMA (Multimarker Analysis of GenoMic Annotation) analysis of the aggregated genetic effects identified NRG1 and ErbB4 as putative genes associated with depression." (PMID 33854034, 2021). "Loss of NRG1 has been related to impaired synaptic plasticity that is in turn associated with chronic stress and depression." (PMID 32703967, 2020). "Low NRG-1 in the cortical projection neurons contributes to increased inhibitory connections and lower synaptic plasticity, eventually increasing the individual’s susceptibility to stress-induced depression and affecting the emotional response in general." (PMID 37710187, 2023). "Conversely, knock down of Nedd4l in the mPFC decreased the degradation of NRG1 and rescued the behavioural changes in CSDS-induced depression-like behaviours, which strongly support that the expression of Nedd4l in the mPFC neurons is required for NRG1 deficiency-mediated susceptibility to stress." (PMID 32703967, 2020). "Absence of response on the 28th day assessed by the HDRS-17 or CGI-I scale among patients with depression might be predicted by alleles of the variant NC_000008.11:g.32614509_32614510del in NRG1 and of the two variants in PIP4K2A: rs61731109 and rs10508649." (PMID 33193575, 2020). "NRG1 SNPs have also been associated with depression and bipolar disorder." (PMID 25762938, 2015). "Hence, NRG-1 deficiency within the cortical projection neurons results in increased inhibitory connections, which is consequently associated with chronic stress and depression." (PMID 37710187, 2023). "Therefore, as a measure of depression-like behaviour, decreased levels of NRG1 in the mPFC could be an important factor affecting an individual’s susceptibility to stress-induced depression and contributes to the modulation of emotional responses." (PMID 32703967, 2020). "We’ve identified a deficiency of NRG1 in the mPFC as a key factor that contributes to the regulation of stress susceptibility in mice, as further suggested by the finding that overexpression of NRG1 attenuated depression-like behaviours in the animal model of chronic social defeat stress (CSDS)." (PMID 32703967, 2020). "The present study showed that multiple pontine genes, including Anxa1, Serpinf1, Arrb1, Cplx2, Nrg1, and Psen1 were altered in a model of depression." (PMID 39135796, 2024). "In short, we demonstrate a role of the NRG1-ErbB4 signaling in the development and expression of depression-like behaviors in response to social stress, and reveal an unexpected mechanism by which the LDTg-VTA circuit regulates VTA DA neuron activity." (PMID 33990773, 2023). "The sensitivity of serum NRG1 as a predictor for depression pre- and post-operative was 92.45% and 52.94% respectively." (PMID 37710187, 2023). "The sensitivity and specificity of serum NRG1 for the prediction of depression in obese persons have been determined by plotting a receiver-operating characteristic (ROC) curve." (PMID 37710187, 2023). "Next, we studied the impact of increasing NRG1 level in LDTg on CSDS-induced depression-like behaviors by injecting AAV-CMV-NRG1-GFP (vNRG1) into LDTg of wild type (WT) mice." (PMID 33990773, 2023).
depression (continued). "NRG-1 is a possible biomarker for the diagnosis of depression pre-bariatric surgery and the prediction of its prognosis post-operatively." (PMID 37710187, 2023). "In the current study, we aimed to investigate the role of neuregulin-1 as a potential blood biomarker linking depression to obesity among obese subjects assigned for laparoscopic sleeve gastrectomy." (PMID 37710187, 2023). "The sensitivity of serum NRG1 as a predictor for different levels of depression pre- and post-LSG has been estimated to be 92.45% and 52.94% respectively while its is 69.09% and 79.73% respectively at cut-off values of ≤3.5 and ≤2.5 ng/ml." (PMID 37710187, 2023). "Nevertheless, both NRG1 and ERBB4 are among the 269 risk genes identified by genome-wide association study (GWAS) of 246,363 depression patients." (PMID 33990773, 2023). "Our results demonstrate a critical role of NRG1-ErbB4 signaling in development and expression of depression-like behaviors via inhibiting K+ channels of VTA DA neurons." (PMID 33990773, 2023). "Nedd4l-mediated downregulation of NRG1 in the medial prefrontal cortex induced depression-like phenotypes mice in chronic social defeat stress." (PMID 37061663, 2023). "Our study provides evidence that the NRG1-ErbB4 signaling in the LDTg-VTA circuit is necessary for social stress-induced depression-like behaviors." (PMID 33990773, 2023). "From the observation of our study we suggest that NRG-1 is a possible biomarker for the diagnosis of depression pre-bariatric surgery and the prediction of its prognosis post-operatively." (PMID 37710187, 2023). "CCK-8 assay indicated that the overexpression of NRG-1 significantly increased the cell viability in the CORT-induced cellular model of major depression, indicating the neuroprotective role of NRG-1 in major depression." (PMID 36559001, 2022). "NRG-1 levels were found to be lower in the prefrontal cortex of patients with schizophrenia, indicating its potential involvement in depression." (PMID 36559001, 2022). "The 6 top blood biomarkers with the strongest overall CFE for tracking and predicting both depression and mania, hence bipolar mood disorders, after the first four steps were NRG1, DOCK10, GLS, PRPS1, TMEM161B, and SLC6A4." (PMID 33828235, 2021). "Consistent with our findings, NRG1 (neuregulin 1) has prior evidence as a biomarker for mood disorders, increased in expression in blood in depression, and decreased in expression after antidepressant treatment." (PMID 33828235, 2021). "To determine if the ketamine-mediated amelioration of depression-like behaviors depends on NRG1/ErbB4 signaling in PV inhibitory interneurons, we tested the antidepressant effects of ketamine in the FST using mice, by manipulating NRG1/ErbB4 signaling." (PMID 33627623, 2021). "For low mood state assessment across all subjects in the independent test cohort, the best biomarker was NRG1, increased in expression in low mood, with an AUC of 62 % (p = 6.8E−03), and 64% (p = 3.5E−02) for assessing clinical depression state." (PMID 33828235, 2021). "NRG1 was increased in the peripheral blood of patients with MDD although NRG1 levels were found to be normal or reduced in patients with depression, compared with healthy subjects." (PMID 33854034, 2021). "Overall, we currently explained a possible mechanism by which Nedd4l mediates depression-like behaviours by inducing NRG1 degradation following stress." (PMID 32703967, 2020). "We then investigated the alteration in NRG1 expression after CSDS in brain regions, like mPFC, that are associated with depression." (PMID 32703967, 2020). "Our data strongly indicate that the Nedd4l-mediated downregulation of NRG1 acts as a critical role in depression-like phenotypes of mice in CSDS." (PMID 32703967, 2020). "We therefore here investigated the effect of CSDS, an ethologically consensus model of depression in mice, on the role of NRG1 in depression-like behaviours." (PMID 32703967, 2020).
depression (continued). "To further confirm that Nedd4l is required for NRG1 degradation in depression, we downregulated Nedd4l via the Si-Nedd4l virus in Dex-treated primary cortical neurons." (PMID 32703967, 2020). "We also found a significant association between a specific SNP of gene EPHX2 and depression, as well as SNPs of EPHX2, OXTR, NRG1 with stress symptoms." (PMID 31801286, 2019). "Future research and improvements in depression-related endophenotypes will reveal the utility of NRG1 models in studying comorbidity directly." (PMID 25762938, 2015). "Genes like NRG1, OLFM1, and WDR62, associated with both tumor progression and neuropsychiatric symptoms such as fatigue and depression, highlight the neuroimmune signature as a potential marker of disease severity and a target to mitigate extrahepatic manifestations in chronic hepatitis." (PMID 41347690, 2025). "These properties were demonstrated in a post-stroke depression model, where an increase in dopamine and serotonin levels was observed in the brains of treated rats, along with an upregulation of the NRG-1-mediated MEK/ERK signaling pathway, contributing to more effective treatment of depression." (PMID 40362487, 2025). "Genes such as DBH, WDR62, NRG1, and FER1L4, identified in hepatic and blood immune transcriptomes, were also implicated in a broad range of disorders, including major depressive disorder, autoimmune diseases, and cancer, which have been previously associated with hepatitis." (PMID 41347690, 2025). "This study showed that SNS could downregulate the expression of Nrg1 and Psen1, indicating an improvement in depression, which is consistent with the results of previous studies." (PMID 39135796, 2024). "In contrast, vNRG1-injected mice spent less time in social interaction and consumed less sucrose after subSD, compared with the vNRG1-injected naive mice and vGFP-injected subSD mice, suggesting that NRG1 overexpression in LDTg promotes the development of depression-like behaviors." (PMID 33990773, 2023). "The NRG1 is expressed in the left cortex and subcortex with variable intensity among the six studied samples, suggesting that the NRG1 is a brain-related biomarker that could be informative upon a mental disorder such as depression." (PMID 37583471, 2023). "Moreover, virus-mediated expression of NRG1 in LDTg enhanced subSD-induced depression behaviors, along with increased NRG1 protein in VTA." (PMID 33990773, 2023). "Together, these results indicate that NRG1 in LDTg is necessary and sufficient to induce depression-like behaviors after social defeat stress and suggest that the LDTg-VTA circuit may regulate VTA DA neuron activity by releasing NRG1." (PMID 33990773, 2023). "And dysregulation of the NRG1 level has been observed in different rodent depression models." (PMID 33854034, 2021). "In a rat model of depression, NRG1 was increased in the prefrontal cortex (PFC) and HPF37." (PMID 33854034, 2021). "NRG1 also had a Cox regression OR of 1.17 (p = 2.5E−02) for predicting all future hospitalizations for depression, and an AUC of 87% (p = 1.1E−03) for predicting first year hospitalizations for depression in females." (PMID 33828235, 2021). "To test the impact of NRG1 on depression-like behaviours, we observed CSDS mice to identify individual peculiarities in the neurobiology mechanisms that might potentially underlay chronic stress responses." (PMID 32703967, 2020). "Moreover, several of the top association signals that did not achieve genome-wide significance were in genes of biological interest, most notably NRG1, which merits further investigation into their potential role in depression and antidepressant response." (PMID 25897834, 2015). "However, whether and how abnormal NRG1-ErbB4 signaling contributes to development and/or expression of depression-like behaviors remains unclear." (PMID 33990773, 2023). "Therefore, NRG1 plays a critical role in depression based on its protein levels." (PMID 33854034, 2021).
depression (continued). "We here assessed the regulation of NRG1 by the E3 ubiquitin ligase Nedd4l (neural precursor cell expressed developmentally downregulated 4-like) and investigated whether NRG1 changes in the mPFC might lead to vulnerability to depression-like behaviours." (PMID 32703967, 2020). "SNPs in EPHX2 (rs17466684), OXTR (rs53576) and NRG1 (rs2919375) are also associated with stress symptoms adjusted for ethnicity, religion, marital status, treatment regimens, past obstetric history of GDM, underlying with allergy and asthma and a family history of depression and anxiety." (PMID 31801286, 2019). "Since our previous studies showed an association of the functional SNP rs6265 in the BDNF gene with depression and response to therapy, we decided to extend the investigation and test additional SNPs in the BDNF gene, NGF, and NRG1." (PMID 40869303, 2025). "We showed that NRG1 in the LDTg was increased by CSDS and was required for ErbB4 activation in VTA DA neurons and depression-like behaviors." (PMID 33990773, 2023). "Second, CSDS increased the expression of NRG1 at LDTg; deleting NRG1 in LDTg reduced ErBB4 activation in VTA and CSDS-induced depression-like behaviors." (PMID 33990773, 2023). "Taking these results together, we suggest NRG1 as a potential robust biomarker to differentiate between MDD patients and HCs under different depression-related conditions as well as to follow up the MDD patients' remission." (PMID 37583471, 2023). "The findings presented in this study are the first to examine in detail the function of Nedd4l regulation of NRG1 in the mPFC brain area, and the first to identify its role in CSDS-induced depression." (PMID 32703967, 2020). "These custom SNPs provide excellent coverage of many previously suggested and functionally important candidate genes for depression, anxiety and stress, including NPY5R; ANO2; EPHX2; TPH2; NRG1; LHPP; FKBP5; SDK2; RORA; OXTR; BDNF; HTR2C; TEX51; and PLEKHG1." (PMID 31801286, 2019). "We also examined the relationship of specific symptomatology criteria with measures of NRG1 cleavage using the Bipolar Inventory of Signs and Symptoms Scale (BISS) and the Montgomery Åsberg Depression Rating Scale (MADRS)." (PMID 22590542, 2012). "However, both NRG1 and ERBB4 were among the 269 putative genes identified by GWAS of 246,363 depression patients." (PMID 33990773, 2023). "In this context, the present study is a trial to identify whether NRG-1 can be a blood biomarker that relates obesity to depression and its effect on post-LSG weight reduction and improvement of depression symptoms." (PMID 37710187, 2023). "Interestingly, the NRG1 gene resulted as the most robust biomarker to differentiate between MDD patients' and HCs under different depression-related conditions and as well to follow-up the MDD patients’ remission." (PMID 37583471, 2023). "Overexpression of NRG-1 could reduce the PC12 neuronal cell injury, while knockdown of NRG-1 abolished the protection of AsVI on the CORT-induced cellular model of major depression." (PMID 36559001, 2022). "Consistently, NRG-1 overexpression raised the levels of DA expression and 5-HT, while NRG-1 knockdown decreased 5-HT and DA levels in the CORT-induced cellular model of major depression." (PMID 36559001, 2022). "A number of individual top biomarkers are known to be modulated by medications in current clinical use for treating depression, such as by lithium (NRG1, PRPS1, CD47), antidepressants (SLC6A4, DOCK10, NRG1, CD47) and the nutraceutical omega-3 fatty acids (GLO1, SLC6A4, CD47, GLS, HNRNPDL)." (PMID 33828235, 2021). "Therefore, we speculated that Nedd4l downregulates NRG1 protein level through the ubiquitin-mediated proteolysis system in SS mice subjected to CSDS, finally leading to depression-like phenotypes." (PMID 32703967, 2020).
Cognitive impairment (27 papers, 2012 to 2026). Abnormal cognition is characterized by deficits in thinking, reasoning, or remembering. "In view of the opposite changes of NRG1/ErbB4 and EGF/ErbB1, the expression of hippocampal NRG1/ErbB4 seems to be more directly linked with cognitive deficits in CCH." (PMID 29875654, 2018). "Similarly, interventions can be designed to address the specific cognitive deficits associated with different NRG1 rs3294999 genotypes." (PMID 39518545, 2024). "Intracerebroventricular NRG1 administration could consequently down-regulated epilepsy susceptibility and ameliorated seizure-induced cognitive impairment." (PMID 38388921, 2024). "Besides, previous studies suggested that disturbance of Neuregulin1 (NRG1)/ErbB4 signaling is associated with cognitive impairments, as well as neuronal apoptosis and neuroinflammation in CNS." (PMID 29875654, 2018). "Thus, a variation that attenuates the activity of either NRG1 or PTK2B (human orthologs of Nrg1 and Pyk2) is likely to enhance the cognitive deficits caused by DAO protein." (PMID 23555897, 2013). "Disruption of NRG1-ErbB4 signaling in the parvalbumin-positive interneurons partially contribute to the isoflurane-induced hippocampus-dependent cognitive impairment in aged mice exposed to isoflurane, which can be reversed by exogenous NRG1-β1." (PMID 39959423, 2025). "Blocking hippocampal NRG1/ErbB4 signaling or ablating ErbB4 attenuated synaptic and cognitive deficits." (PMID 38388921, 2024). "To balance epilepsy and additional potential cognitive impairment, we must further explore the appropriate timing and dose of NRG1 administration according to the pathophysiologic state of AD." (PMID 38388921, 2024). "In spinal fluid from mild cognitive impairment (MCI) AD patients, NRG1 levels are increased and associated with cognitive loss." (PMID 37903620, 2023). "Studies recently explain the relation between the pivotal role of NRG-1 and inflammation in the development of the cognitive disorders." (PMID 34484988, 2021). "More specifically, mutations in NRG1/ERBB4 lead to impairments in AMPA and NMDA receptors’ spines structure and plasticity, and it has been attributed to cognitive deficits observed in SCZ patients." (PMID 34946848, 2021). "We previously revealed that a decreased hippocampal PV expression following with a disruption of neuregulin 1-ErbB4 signaling contributed to isoflurane-induced hippocampus-dependent cognitive impairment in aging mice." (PMID 27790135, 2016). "In the present study, we report that an intracerebroventricular infusion of NRG1 attenuated cognitive impairments in 13-month-old Tg2576 mice, an animal model of Alzheimer's disease (AD)." (PMID 26913607, 2016). "In Experiment 4, the chronic administration of valproate successfully rescued the observed cognitive deficits of male TMc-Nrg1+/− mice and hippocampal GAD67 expression." (PMID 24782733, 2014). "Based on the findings of Experiments 1A, 2, and 3B, chronic administration of valproate was used to evaluate the effects of valproate on the rescue of the cognitive deficits that were observed in the male TMc-Nrg1+/− mice." (PMID 24782733, 2014). "NRG1 is abundantly expressed in the hippocampus, and emerging studies have begun to reveal the link between NRG1 signaling and cognitive deficits in schizophrenic patients." (PMID 24782733, 2014). "On the one hand, NRG1-ErbB4 signaling could exert protective effects against cognitive deficits in AD models." (PMID 38388921, 2024). "NRG1 improves neuropathology and cognitive deficits in AD mice." (PMID 37061663, 2023). "It is unclear whether Nrg1 in the brain exerts protective or detrimental effects on cognition as both high and low levels of Nrg1 at synapses lead to cognitive impairment in animal models." (PMID 35338546, 2022). "Upregulation of NRG-1-signaling may be therefore involved in the potential olanzapine-related improvement of some cognitive deficits." (PMID 33801609, 2021).